C1QTNF6 (C1q and TNF related 6)
Diseases named in the same sentence as C1QTNF6 in open-access papers (continued):
Sharing a sentence is not in itself a finding about the gene and the disease.
experimental autoimmune encephalomyelitis (1 paper, 2015). An autoimmune demyelinating disease of the central nervous system that is produced experimentally in animals by the injection of homogenized brain or spinal cord in Freund's adjuvant. "The Arthus reaction and the development of experimental autoimmune encephalomyelitis are also enhanced in C1qtnf6−/− mice and C1qtnf6−/− embryos are semi-lethal." (PMID 26404464, 2015).
glioma (1 paper, 2025). A benign or malignant brain and spinal cord tumor that arises from glial cells (astrocytes, oligodendrocytes, ependymal cells). "Additionally, patients with glioma with higher C1qtnf6 expression demonstrated higher TIDE scores, suggesting a potentially beneficial response to immune checkpoint blockade (ICB) treatment." (PMID 40490027, 2025).
ischemia (1 paper, 2022). A hypoperfusion of the BLOOD through an organ or tissue caused by a PATHOLOGIC CONSTRICTION or obstruction of its BLOOD VESSELS, or an absence of BLOOD CIRCULATION. "Secondly, miR-29b plays imperative roles as a downregulatory of C1QTNF6 in leukocytes, leading to reduction in ischemia-induced inflammatory response, BBB disruption, and ultimately infarct volume." (PMID 36052307, 2022).
Listeria infection (1 paper, 2021). "Eight of these genes were similarly inhibited by Listeria infection in PMH: they encode (i) the activating enzyme C1S of the C1 complex, (ii) the central component C3, (iii) the membrane-attack proteins C6 and C8A, and (iv) four complement regulators (C1QTNF6, CFH, CFHR2, VTN)." (PMID 34858876, 2021).
lung diseases (1 paper, 2025). "However, to fully assess its specificity, future studies should investigate whether C1qtnf6 expression is also elevated in nonmalignant lung diseases, such as COPD or pulmonary fibrosis, to determine its potential diagnostic boundaries." (PMID 40490027, 2025).
macular degeneration (1 paper, 2022). Loss of vision in the central portion of the retina (macula), secondary to retinal degeneration. "Furthermore, miRNA hsa-29a-3p plays a role in structure regulation, specifically regulating the synthesis of different collagen chains, and HMCN1 (hemicentin 1) is involved in macular degeneration and C1QTNF6 (C1q and TNF related 6) is involved in identical protein binding activity." (PMID 36114255, 2022).
prostate carcinoma (1 paper, 2023). A carcinoma that arises from epithelial cells of the prostate gland. "Our results suggest that C1QTNF6 may promote cancer proliferation and migration also in prostate cancer." (PMID 36809527, 2023).
Stroke (1 paper, 2022). Sudden impairment of blood flow to a part of the brain due to occlusion or rupture of an artery to the brain. "Consistent with the previous findings, we found that C1QTNF6 is among the target genes of miR‐29b, and is significantly downregulated in leukocytes of stroke patients and MCAO rats." (PMID 35322553, 2022). "H19 and C1QTNF6 upregulation, as well as miR‐29b downregulation, was detected in leukocytes of patients with stroke." (PMID 35322553, 2022). "There was a negative linear correlation between miR‐29b and C1QTNF6 levels in the neutrophils of patients with stroke (r = −0.716, p < 0.001)." (PMID 35322553, 2022).
cancer (20 papers, 2019 to 2025). A tumor composed of atypical neoplastic, often pleomorphic cells that invade other tissues. "Many cancer types overexpress C1qtnf6, and many malignancies have C1qtnf6 linked to numerous traditional pathways, including epithelial–mesenchymal transformation (EMT) and angiogenesis." (PMID 40490027, 2025). "To screen the key genes, we analyzed them using the GSCA database, which showed that high expression of KRT80 and C1QTNF6 in cancer tissues was significantly associated with the overall survival of the samples." (PMID 39247607, 2024). "We further explored the correlation between the C1QTNF6 gene and genes associated with immune cells in pan-cancer." (PMID 35401204, 2022). "A value of Hazard ratio greater than 1 indicates a risk prognostic factor, it is found that C1QTNF6 predicts poor survival in most cancers." (PMID 35401204, 2022). "Our study provides the mutation landscape of C1QTNF6 in pan-cancer and the correlation landscape with copy number variation and methylation." (PMID 35401204, 2022). "Besides, we also identified a positive correlation between C1QTNF6 and cancer hallmark pathway score, tumor microenvironment related pathways score (TMEp score), and immune characteristic." (PMID 35401204, 2022). "Therefore, monitoring the expression level of C1QTNF6 may be an effective diagnostic method for these cancers." (PMID 35401204, 2022). "Combining with the C1QTNF6 expression and its drug sensitivity analysis (positively correlated and negatively correlated), we may establish risk stratification for cancer patients, which optimize the development and application of anti-cancer drugs." (PMID 35401204, 2022). "This study revealed that C1qtnf6 is consistently upregulated in several human cancers, which is consistent with previous analyses." (PMID 40490027, 2025). "Pan‐cancer analyses using TCGA data showed that C1qtnf6 was significantly upregulated in many tumors, including BLCA, BRCA, STAD, and LUAD, compared with the corresponding normal tissues." (PMID 40490027, 2025). "High-risk genes (C1QTNF6, LDHA, IGF2BP1) resulted in poor clinical outcomes by promoting cancer cell metabolism and proliferation." (PMID 36032673, 2022). "Subsequently, we explored the association between C1QTNF6 and copy number mutation (CNA) in pan-cancer." (PMID 35401204, 2022). "Next, GSEA was performed for the purpose of further examining the association of various pathways, especially immune-related pathways, with C1QTNF6 in pan-cancer." (PMID 35401204, 2022). "Here, bioinformatics analysis was conducted for the purpose of comprehensively examining the significance of C1QTNF6 in pan-cancer by combining GTEx and TCGA data." (PMID 35401204, 2022). "The expression level of C1QTNF6, as well as its prognostic significance in pan-cancer, was explored." (PMID 35401204, 2022). "Amongst, the biological role of C1QTNF6 in malignant tumors has become a hot research topic in recent years." (PMID 35879698, 2022). "According to the findings of the present research, C1QTNF6 serves a prominent function in the immune milieu of cancer cells." (PMID 35401204, 2022). "The role of C1QTNF6 in tumor cell survival and cell cycle has been investigated in cancers other than OSCC." (PMID 34906149, 2021). "This evidence suggests a potential regulatory role of C1QTNF6 in tumorigenesis, which emphasizes the need for further study of the function and mechanism of C1QTNF6 in other cancers." (PMID 34906149, 2021). "When examining C1qtnf6 expression across 23 types of tumors and their matched normal tissues, the results were largely consistent with those of the unmatched samples, confirming the widespread upregulation of C1qtnf6 in cancer tissues." (PMID 40490027, 2025). "Based on these results, C1qtnf6 could be a viable target for cancer treatment and could aid in the study of the processes underlying anticancer drug resistance." (PMID 40490027, 2025). "Upregulation of C1qtnf6 expression is observed in various human cancers." (PMID 40490027, 2025).
cancer (continued). "The prognostic risk model based on six DMGs in our study, namely FAM83A, S100A16, E2F7, ANLN, C1QTNF6 and GAPDH, suggests that they might reveal causes of the cancer development and tumorigenesis in LUAD." (PMID 38711158, 2024). "We found that C1QTNF6 is positively correlated with most cancer super-pathways." (PMID 35401204, 2022). "C1QTNF6 was differentially expressed in 26 cancers in the TCGA cohort." (PMID 35401204, 2022). "Many studies have preliminarily elucidated the role of C1QTNF6 in cancer." (PMID 35401204, 2022). "Overall, we identified the value of C1QTNF6 in pan-cancer by multiple analyses." (PMID 35401204, 2022). "In this study, we explore the role of C1QTNF6 with comprehensive means using TCGA pan-cancer data." (PMID 35401204, 2022). "Then, we explored the correlation between C1QTNF6 and methylation in pan-cancer." (PMID 35401204, 2022). "Subsequently, we investigated the prognostic significance of C1QTNF6 in pan-cancer." (PMID 35401204, 2022). "Collectively, these results emphasize the in vivo promoting role of C1QTNF6 in cancer progression." (PMID 34906149, 2021). "Furthermore, although C1qtnf6 expression is elevated in various cancer types, its unique pattern of elevated expression in LUAD suggests that it may offer specific prognostic insights in this cancer type." (PMID 40490027, 2025). "Therefore, C1QTNF6 might serve an instrumental function in the occurrence and progression of cancer." (PMID 35401204, 2022). "In addition, the molecular mechanisms involved in the elevated expression of C1QTNF6 in BC may require further investigation of related cancer pathway(s) as well as in vivo analyses." (PMID 33123583, 2020). "C1QTNF6 (CTRP6), a member of the CTRP family, has recently been implied to play a role in the tumorigenesis of for a variety of cancer types." (PMID 34906149, 2021). "C1q/tumor necrosis factor-related protein 6 (C1QTNF6), a member of the C1q/tumor necrosis factor-related protein (CTRP) family, has been revealed to play a role in carcinogenesis and cancer progression." (PMID 33269376, 2021). "We found that C1QTNF6 was strongly correlated with TME related pathways, such as EMT1, base excision, and mismatch repair pathways correlated with the onset and progression of cancer." (PMID 35401204, 2022). "To determine whether C1QTNF6 may have a role in OSCC, we downloaded and analyzed data from 40 paired cancer and normal tissues from The Cancer Genome Atlas (TCGA)." (PMID 34906149, 2021). "Based on our findings, we speculate that C1QTNF6 knockdown leads to complex changes in OSCC, which produces an anti-cancer effect through acute phase response both in vivo and in vitro." (PMID 34906149, 2021). "Interestingly, the genes CDC20, CDCA8, MYBL2, C1QTNF6, CEP55, CDK1 and KIF14 were found to be more universal/common, since they mark multiple types of cancers not only in prognosis but also in diagnosis." (PMID 32489468, 2020). "However, there has not been a comprehensive analysis of the significance of C1QTNF6 in cancer." (PMID 35401204, 2022).
tumor (16 papers, 2015 to 2025). "It has been demonstrated that C1qtnf6 expression is closely associated with the tumor immunological milieu, immune checkpoint blockade (ICB), and response to cisplatin treatment." (PMID 40490027, 2025). "In this study, we hypothesized that high C1qtnf6 expression in LUAD promotes tumor progression and is associated with poor prognosis, thus being able to potentially serve as a prognostic marker and therapeutic target in LUAD." (PMID 40490027, 2025). "C1qtnf6 expression was favorably correlated with tumor mutational burden (TMB) scores." (PMID 40490027, 2025). "Moreover, the tumor biological and immunological characteristics of C1QTNF6 were clarified in the forms of the correlation between C1QTNF6 expression and hallmark Pathway scores in MsigDB database, immune cell infiltration, immune-related genes." (PMID 35401204, 2022). "In this study, we analyzed The Cancer Genome Atlas (TCGA) and found that C1QTNF6 might be a potential tumor-associated regulator involved in the carcinogenesis of OSCC." (PMID 34906149, 2021). "Furthermore, we investigated the correlation between C1qtnf6 expression and immune cell infiltration across different tumor types, which revealed notable associations with specific immune cell types, suggesting a potential role for C1qtnf6 in modulating the tumor immune microenvironment." (PMID 40490027, 2025). "This discovery expands our understanding of the role of C1qtnf6 in the tumor microenvironment and provides new evidence for its potential as an immune‐targeted therapeutic candidate for LUAD." (PMID 40490027, 2025). "In this study, we examined the mRNA expression of C1qtnf6 in pan‐tumor tissues and the equivalent nearby normal tissues using TCGA and GTEX datasets." (PMID 40490027, 2025). "C1QTNF6, as a promising prognostic biomarker, manifests its promising prospect in immunoregulation and a potential target for tumor therapy." (PMID 35401204, 2022). "MiR‐29a-3p, a newly discovered tumor-related intergenic miRNA, has been predicted as a potential key regulator of C1QTNF6 by bioinformatics analysis." (PMID 35879698, 2022). "We further found the role of C1QTNF6 in the tumor microenvironment (TME), including the correlation between C1QTNF6 and the immunosuppressive genes, immune cell infiltration score, chemokines, and chemokine receptors." (PMID 35401204, 2022). "The effect of C1QTNF6 knockdown on in vivo tumorigenicity of OSCC cells in vivo was evaluated using nude mouse xenograft tumor model." (PMID 34906149, 2021). "To extend the in vitro observations, we investigated the effects of C1QTNF6 knockdown on tumor growth in vivo." (PMID 34906149, 2021). "C1QTNF6 is a crucial molecular mediator of inflammation, fibrosis, and metabolism, and it has also been implied in the involvement of tumor development." (PMID 34906149, 2021). "To extend the in vitro observations, we investigated the effect of C1QTNF6 knockdown on tumor growth in vivo and observed that C1QTNF6 silencing suppressed tumor growth in mice." (PMID 34906149, 2021). "Cal-27 cells that were transfected with either C1QTNF6-shRNA or Ctrl-shRNA lentivirus were injected into nude mice, and the tumor growth was monitored." (PMID 34906149, 2021). "To test this hypothesis, we systematically analyzed C1qtnf6 expression in LUAD and its relationship with immune infiltration, the tumor microenvironment, and patient survival rate to further explore the clinical value of C1qtnf6 as a prognostic indicator." (PMID 40490027, 2025). "Besides, our study found a significant positive correlation between C1QTNF6 and angiogenesis, which is of reference value for us to further explore the mechanism of tumor angiogenesis and develop new therapeutic methods." (PMID 35401204, 2022).
tumor (continued). "Our results demonstrated that the mRNA expressions of IL-5, IL-1A, CXCL10, TNFSF4 and INHBE were significantly altered when regulating C1QTNF6, which suggested the essential implications of the cytokine-cytokine receptor interaction pathway in the process of C1QTNF6 regulating tumor progression." (PMID 35879698, 2022). "The results suggest that C1QTNF6 tends to be more highly expressed in OSCC, indicating that it could potentially be a tumor-associated regulator involved in the carcinogenesis of OSCC." (PMID 34906149, 2021). "The arrow represents TUNEL-positive cells, the results suggested that down-regulated C1QTNF6 expression could significantly promote tumor cell apoptosis, while C1QTNF6 overexpressed inhibited the tumor cell apoptosis in vivo relative to the control group." (PMID 33269376, 2021). "Moreover, RNA sequencing analysis demonstrated that the cytokine-cytokine receptor interaction pathway may participate in the process of C1QTNF6 regulating tumor progression." (PMID 35879698, 2022). "Besides, C1QTNF6 is obviously correlated with many immune checkpoints including LAG3, PDCD1, CTLA4, which suggested that C1QTNF6 may act as a new immune checkpoint for tumor immunity." (PMID 35401204, 2022). "In addition, down-regulation of C1QTNF6 weakened the tumor growth in vivo." (PMID 33269376, 2021). "However, up-regulation of C1QTNF6 promoted the tumor growth and weight." (PMID 33269376, 2021). "Furthermore, knockdown of C1QTNF6 in Cal-27 cells inhibited tumor growth of OSCC in vivo." (PMID 34906149, 2021). "C1qtnf6/Ctrp6, a member of C1q/TNF-related protein (CTRP) family, was demonstrated to increase the synthesis of IL-10 macrophages and promote tumor neovascularization." (PMID 38994368, 2024). "Therefore, C1QTNF6 might perform an integral function in tumor progression." (PMID 35401204, 2022). "In the present study, the experiments suggested that ectopic expression of C1QTNF6 significantly promoted cell proliferation of SPCA1 and A549 cells and tumor growth in vivo." (PMID 33269376, 2021). "Moreover, down-regulation of C1QTNF6 could weaken the tumor growth and apoptosis in vivo." (PMID 33269376, 2021). "We performed C1QTNF6 knockdown in OSCC cell lines and xenografted tumors to explore the pathological relevance between C1QTNF6 expression and OSCC, including its potential role in the proliferation and apoptosis of OSCC cells in vitro and tumor growth in vivo." (PMID 34906149, 2021). "Therefore, our microarray analysis results fit well with the known effects of signaling pathways and genes on tumorigenesis, suggesting that the promotion of tumor development by C1QTNF6 might be mediated through regulation of Acute Phase Response signaling and ID1, BBC3, and DDIT3 gene expression." (PMID 34906149, 2021).
infection (4 papers, 2021 to 2023). The state of being infected such as from the introduction of a foreign agent such as serum, vaccine, antigenic substance or organism. "RT-qPCR assays was employed to measure the expression level of C1QTNF6 in NSCLC cells after infection, si-C1QTNF6 markedly down-regulated C1QTNF6 expression and pc-C1QTNF6 up-regulated C1QTNF6 expression compared with the controls." (PMID 33269376, 2021). "In addition, the expression of c1r, c6, c1qbp and c1qtnf6 in MOS200 or MOS400 groups were higher than that of the control group before or post-infection, which revealed the activation of these genes by dietary MOS and might enhance the anti-infection immunity of M. amblycephala intestines." (PMID 36768530, 2023).
adenocarcinoma (1 paper, 2023). A common cancer characterized by the presence of malignant glandular cells. "Moreover, univariate overall survival analysis of these individual 10 genes overexpressed in adenocarcinoma revealed a dramatic prognosis, the worst being C1QTNF6 and PROM2 overexpression." (PMID 38132167, 2023).
respiratory diseases (1 paper, 2025). "J. Wang revealed that miR-29b-3p modulated particulate matter-induced inflammatory responses via the C1QTNF6/AMPK pathway, which provided new insights into the molecular mechanisms behind chronic inflammation in respiratory diseases." (PMID 40270961, 2025).
C1QTNF6 also shares sentences with these, for which no sentence is quoted: Obesity (10 papers); Hypertension (6); diabetes (4); metabolic disorders (4); heart failure (3); Insulin resistance (3); type 2 diabetes mellitus (3); age-related macular degeneration (2); colon cancer (2); diabetic nephropathy (2); diffuse gastric adenocarcinoma (2); endothelial dysfunction (2); Gestational Diabetes Mellitus (2); head and neck squamous cell carcinoma (2); cardiac hypertrophy (1); cardiovascular diseases (1); cavernous hemangioma (1); Cognitive impairment (1); colon adenocarcinoma (1); colorectal cancer (1); coronary artery disease (1); endotoxemia (1); Glucose intolerance (1); hypertrophy (1); infectious disease (1); infertile (1); inflammatory bowel disease (1); Kawasaki disease (1); melanoma (1); metabolic syndrome (1).
A further 19 diseases each share a sentence with C1QTNF6 in 1 paper.